MAPKAPK5-AS1 (MAPKAPK5 antisense RNA 1)
Synonyms: C12orf47; FLJ39616; MAAS; lncRNA-cCSC1
Gene: Long non-coding RNA gene on chromosome 12 (111,839,758 to 111,842,902, reverse strand). Ensembl gene ENSG00000234608.
Diseases named in the same sentence as MAPKAPK5-AS1 in open-access papers:
MAPKAPK5-AS1 is named in the same sentence as 2 diseases in open-access papers, as found by Europe PMC text mining. Sharing a sentence is not in itself a finding about the gene and the disease. The quoted sentences say what the papers report.
tumor (2 papers, 2020 to 2025). "MAPKAPK5 antisense RNA 1 (MAPKAPK5-AS1, ENSG00000234608), one of 4 HCC prognosis-related lncRNAs, was differentially expressed between HCC tissues and adjacent non-tumor tissues and negatively associated with OS of HCC patients." (PMID 32368296, 2020).
MAPKAPK5-AS1 also shares sentences with these, for which no sentence is quoted: Neonatal sepsis (1 paper).